OR2T1 (olfactory receptor family 2 subfamily T member 1)
Description:
Odorant receptor.
Synonyms: OR1-25
Gene: Protein-coding gene on chromosome 1 (248,403,048 to 248,408,020, forward strand). Ensembl gene ENSG00000175143.
Subcellular location: Cell membrane
Pathways (Reactome):
Sensory Perception: Expression and translocation of olfactory receptors; Olfactory Signaling Pathway
Genetic constraint (gnomAD): Loss-of-function variants: 1 observed, 0.68 expected, observed/expected ratio (o/e) 1.47, 90% interval 0.31 to 1.92. That is too few expected variants to judge how well the gene tolerates losing a copy. Missense variants: 440 observed, 411.92 expected, observed/expected ratio (o/e) 1.07, 90% interval 0.99 to 1.16. Synonymous variants: 186 observed, 154.09 expected, observed/expected ratio (o/e) 1.21, 90% interval 1.07 to 1.36.
Homologues: Orthologues: macaque OR2T1 (95% identical), dog OR2T1 (92% identical), pig OR2T1 (91% identical), guinea pig OR2T1 (88% identical), mouse Or2t1 (86% identical), rat Or2t1 (86% identical). Paralogues in human: OR2T6 (70% identical), OR2T27 (69% identical), OR2T2 (66% identical), OR2T35 (66% identical), OR2T11 (64% identical), OR2T5 (61% identical), OR2T29 (61% identical), OR2T4 (59% identical), OR2T10 (58% identical), OR2T33 (53% identical), OR2T12 (53% identical), OR2V2 (53% identical), and 80 more.